BTBD18 (BTB domain containing 18)
Description:
Specifically required during spermatogenesis to promote expression of piRNA precursors. The piRNA metabolic process mediates the repression of transposable elements during meiosis by forming complexes composed of piRNAs and Piwi proteins and governs the methylation and subsequent repression of transposons, which is essential for the germline integrity. Acts by facilitating transcription elongation at piRNA loci during pachytene.
Tractability: Antibody: the Human Protein Atlas places it where antibodies can reach.
Gene: Protein-coding gene on chromosome 11 (57,743,514 to 57,753,148, reverse strand). Ensembl gene ENSG00000233436.
Subcellular location: Nucleus
Subcellular location (Human Protein Atlas): Nucleoplasm; Plasma membrane; Vesicles
Gene Ontology:
Molecular function: protein binding
Biological process: male meiosis I; piRNA transcription; spermatogenesis; transposable element silencing; positive regulation of transcription elongation by RNA polymerase II
Cellular component: nucleus
Genetic constraint (gnomAD): Loss-of-function variants: 0 observed, 6.81 expected, observed/expected ratio (o/e) 0, 90% interval 0 to 0.44. That is too few expected variants to judge how well the gene tolerates losing a copy. Missense variants: 787 observed, 885.02 expected, observed/expected ratio (o/e) 0.89, 90% interval 0.84 to 0.94. Synonymous variants: 311 observed, 342.48 expected, observed/expected ratio (o/e) 0.91, 90% interval 0.83 to 1.
Homologues: Orthologues: chimpanzee BTBD18 (99% identical), macaque BTBD18 (96% identical), dog BTBD18 (83% identical), pig BTBD18 (83% identical), rabbit BTBD18 (80% identical), rat Btbd18 (77% identical), mouse Btbd18 (76% identical), guinea pig BTBD18 (58% identical). Paralogues in human: KBTBD11 (12% identical), KLHDC7A (12% identical), KLHL22 (11% identical), KLHL21 (10% identical), KLHL20 (10% identical), KLHL4 (10% identical), KLHDC7B (10% identical), KLHL1 (10% identical), KLHL14 (10% identical), KLHL26 (10% identical), KLHL13 (10% identical), KLHL17 (10% identical), and 42 more.
Diseases named in the same sentence as BTBD18 in open-access papers:
BTBD18 is named in the same sentence as 3 diseases in open-access papers, as found by Europe PMC text mining. Sharing a sentence is not in itself a finding about the gene and the disease. The quoted sentences say what the papers report.
Obesity (1 paper, 2016). Accumulation of substantial excess body fat. "An application to the UK10K data reveals novel rare variants in gene BTBD18 associated with childhood onset obesity." (PMID 27152526, 2016). "We identified a gene, BTBD18, that passes the exome-wide significance threshold and that is also a plausible candidate for childhood onset obesity." (PMID 27152526, 2016). "As gene BTBD18 has also been found to over-express in obese children elsewhere (NCBI GEO Profile ID: 64932244), it makes a plausible candidate for childhood onset obesity." (PMID 27152526, 2016).
BTBD18 also shares sentences with these, for which no sentence is quoted: heart defects (1 paper); Onset (1).